IL6 (interleukin 6)
Diseases named in the same sentence as IL6 in open-access papers (continued):
Sharing a sentence is not in itself a finding about the gene and the disease.
colitis (continued). "In our study, the increase in adipose tissue inflammation seen in the Colitis + HFD group was confirmed by the increase in CLS, activated macrophages, lymphocytes and neutrophils and the overexpression of adhesion molecules, TNFα, IL-6, MCP1/CCL2 and TLR4." (PMID 22073943, 2011). "In genetic complementation studies, we found functional redundancy between the IL6 and IL11 signaling in intestinal epithelium, where both cytokines were equally potent in conferring Stat3-dependent, epithelial resistance to DSS-induced apoptosis and colitis." (PMID 20478049, 2010). "Interestingly, inflammatory mediators in colonic cultures from colitic DKO mice were similar to those found in colon tissue during acute C. rodentium-induced colitis: TNF-α, IFN-γ, IL-1β, IL-17, and IL-6." (PMID 20976045, 2010). "The colitis, developed after TNBS administration, largely enhanced the expression of TNF-α, IL-6, IL-1β, IL-12, IL-23, IL-17, Cox-2, IL-10, and IFNβ genes, with a fold increase in mRNA levels of 28.7, 89.26, 303.9, 36.03, 9.14, 329.00, 32.07, 10.89, and 24.16, respectively compared to healthy mice." (PMID 17375199, 2007). "Moreover, SN38-PLGA markedly alleviated colitis severity, as demonstrated by improved body weight, increased colon length, reduced disease activity and histological scores, and lower serum levels of TNF-α, IL-1β, and IL-6 compared with free SN38 or saline." (PMID 42099549, 2026). "Furthermore, in a DSS‐induced colitis mouse model, UMSC treatment decreased the proportion of Th1 and Th17 cells and down‐regulated the expression of inflammatory cytokines, including IFN‐γ, IL‐1β, IL‐6, IL‐17, as well as TNF‐α at the mRNA levels." (PMID 40842289, 2025). "Furthermore, HD-SD treatment significantly ameliorated the disease severity of acetic acid (AA)-induced colitis in rats, as evidenced by improved clinical signs, attenuated histological damage, and decreased levels of inflammatory factors (TNF-α, IL-6, and IL-1β)." (PMID 41008224, 2025). "In vivo studies demonstrated that AOE reduced DSS-induced colitis in mice by increasing the colon length, enhancing antioxidant enzyme activity, inhibiting inflammatory cell infiltration, suppressing the formation of TNF-α and IL-6, and reducing malondialdehyde (MDA) levels." (PMID 39857378, 2025). "Together, these findings suggest that repeated mosquito biting prior to colitis induction does not exacerbate acute inflammation but may instead influence recovery by modulating neutrophil activity and IL-6–mediated responses." (PMID 41367418, 2025). "Furthermore, the SOD3-mediated, anti-inflammatory role in skin inflammation by inhibiting the expression of proinflammatory cytokines, including TNF-α, IL-1β, IL-6, and IL-8, and SOD1-mediated suppression of proinflammatory immune responses against oxidative stress in colitis, were also reported." (PMID 40825682, 2025). "I3C did not alter TNF-α and IL-12 in male and female mice but increased the IL-1β and IL-6 in male mice and decreased IFN-γ in female and male mice, suggesting that I3C ameliorates colitis in females but not in males, indicating that I3C sex-specifically exhibits anti-colitis activity in mice." (PMID 40094833, 2025). "DHNA also inhibited the production of IL-6 in bone marrow macrophages upon exposure to LPS without showing toxicity for these cells, so it could represent a nontoxic Ahr activator for colitis prevention." (PMID 40563526, 2025). "In vivo studies using a DSS-induced colitis mouse model further demonstrated that HME-MUL-F2 could alleviate colitis symptoms, increase body weight and colon length, reduce pro-inflammatory cytokines (IL-1β, TNF-α, IL-6, MCP-1), and increase anti-inflammatory cytokines (IL-10)." (PMID 40283912, 2025).
colitis (continued). "Notably, NINJ1 deficiency enhances lung cancer cell motility by upregulating ICAM-1 through the IL-6/STAT3 signaling pathway, while its overexpression suppresses colitis-mediated colon cancer growth by inhibiting macrophage migration and invasion via the repression of FAK signaling." (PMID 40075648, 2025). "Indeed, our prior preliminary work indicated that A. bisporus WMP pretreatment could reduce IL‐1β and IL‐6, and MPO activity in the proximal colon of a murine DSS‐induced colitis model." (PMID 40509652, 2025). "Spirulina platensis (SP) and Dunaliella salina (DS) were investigated on acetic acid-induced colon inflammation in rats, and both microalgae demonstrated anti-inflammatory properties by inhibiting the production of proinflammatory cytokines such as IL-1β, TNF-α, and IL-6." (PMID 39195452, 2024). "The PCA has been reported to inhibit the production of inflammatory mediators, such as IL-6, TNF, IL-1β, and prostaglandin E2 (PGE2), potentially by suppressing the activation of NF-κB and extracellular signal-regulated kinase (ERK) in murine BV2 microglia cells and colitis mouse model." (PMID 38998493, 2024). "Furthermore, protocatechuic acid-treated mice exhibited a reduction in the expression of proinflammatory cytokines (IL-6, IL-1β, TNF-α, and cyclooxygenase 2 (COX-2)) in TNBS-induced colitis, achieved by modulating the sphingosine kinase (SphK)/S1P and related signaling pathways." (PMID 38732594, 2024). "To gain a deeper understanding of the mechanism by which TP2 alleviates colitis, we utilized ELISA technology to assess typical pro-inflammatory and anti-inflammatory cytokines in rats’ colonic tissues, including TNF-α, IFN-γ, IL-1β, IL-6, IL-10, IL-17A, IL-22, and IL-23." (PMID 39776580, 2024). "Our results demonstrated that the cecal gene expression of IL-6, CXCL2 (murine IL-8 homologue), IL-1β, TNF-α, IL-17a, IL-22, and CRAMP (homologue of human cathelicidin LL-37) was significantly elevated in the mice with P. aeruginosa-infected colitis after chemotherapy." (PMID 38397855, 2024). "EcN-TNFaNb and EcN-IL10 demonstrated effective mitigation of DSS-induced mouse colitis, as indicated by reduced colon length shortening, lower disease activity index (DAI), and altered expression of pro-inflammatory cytokines in colon tissues, such as TNF-α, IL-6, IL-17 A, and MCP-1." (PMID 38739270, 2024). "Treatment with L. casei IB1 improved DSS-induced colitis in mice, as indicated by increased body weight, colon length, and goblet cell numbers and decreased disease activity index (DAI), proinflammatory factor (TNF-α, IL-1β, and IL-6) levels, and histopathological scores after intake of IB1." (PMID 39065147, 2024). "In addition, in vitro treatment of colonic epithelial cells with AmEVs reduced the production of IL-6, and oral administration of AmEV to mice alleviated DSS-induced colitis phenotypes such as inflammatory cell infiltration, weight loss, and shortened colonic length." (PMID 39741950, 2024). "Moreover, another study also proposed that ginsenosides Rd was able to effectively alleviate DSS colitis in mice through inhibiting proinflammatory cytokines expression (TNF-α, IFN-γ, IL-6, IL-12/23p40, and IL-17A) and inhibiting NF-κB and P38MAPK signaling pathways." (PMID 38698858, 2024). "Chlorogenic acid, at concentrations of 1 mM or 20 mg/kg, markedly reduced the release of IFN-γ, TNF-α, and IL-6 and the infiltration of F4/80+ macrophages, CD3+ T cells, and CD177+ neutrophils into the colon by blocking the activated NF-κB signaling pathway in DSS-induced colitis." (PMID 38732594, 2024). "Furthermore, L. edodes polysaccharides have been shown to mitigate weight loss and reduce the expression of pro-inflammatory cytokines such as TNF-α, IL-6, IL-1β and IFN-γ in DSS-induced colitis in mice, suggesting their potential therapeutic efficacy in colitis treatment." (PMID 39130633, 2024).
colitis (continued). "In addition, other authors also demonstrated that a new polysaccharide isolated from HE (HEP10) suppressed the LPS/DSS-induced production of iNOS and COX-2 and proinflammatory mediators such as TNF-α, IL-6 and IL-1β, as well as NLRP3 inflammasome, in rodent models of colitis and in macrophages." (PMID 38671931, 2024). "In alcohol-induced colon inflammation, a polyphenol-rich extract of Zhenjiang aromatic vinegar was shown to increase IL-10 and IL-22 levels in the colon of ICR (Institute of Cancer Research) mice exposed to ethanol and also to reduce TNF-α, IL-6, IL-1β, and LPS levels." (PMID 38247489, 2024). "Daucosterol was able to significantly attenuate dextran sulfate sodium-induced colitis and prevent the development of colorectal cancer by reducing ROS production, macrophage infiltration, expression of pro-inflammatory factors such as TNF-α and IL-6/1β, and increasing NK cell activity." (PMID 38324023, 2024). "Expression of NF-κB, TLR4, Myd88, and downstream molecules such as TNF-α, IL-6, and IL-1β was effectively reduced by SGP-H, which improved the secretion of anti-inflammatory cytokines including IL-20 and IL-10 in the colon tissue and serum of DSS-induced colitis mice." (PMID 37836386, 2023). "Considering that IL-6 expression was upregulated in naïve Cldn3KO mice, we further examined whether the production of TNF-α, a proinflammatory cytokine targeted in treating IBD, is also altered in Cldn3KO mice under conditions of colitis." (PMID 38010872, 2023). "The qRT-PCR assays revealed that all serum IL-6, tumor necrosis factor α (TNF-α), and zonulin level at the mRNA levels significantly increased in the DSS-induced mice colitis relative to the WT group, which could be relieved by adding matrine in their drinking water (P < .05)." (PMID 37326155, 2023). "Oral NPs-PEG-FA/6-shogaol can downregulate the proinflammatory factors (TNF-α, IL-6, IL-1β and iNOS), upregulate the expression level of anti-inflammatory factors (Nrf-2 and HO-1), alleviate the colitis symptoms and accelerate the wound repair of DSS-induced colitis mice." (PMID 37033644, 2023). "In the DSS-induced colitis mouse model, oral administration of bioactive compounds of P. oleracea extract (portulacanone C, cis-n-feruloyl-3′-methoxytyramine, and trans-n-feruloyltyramine) and 3% DSS led to significant reduction of cytokine levels such as TNF-α, IL-6, 1L-1β, IL-4, IL-17, and IFN-γ." (PMID 37693918, 2023). "Additionally, POL has been shown to effectively attenuate DSS-induced colitis by inhibiting oxidative stress responses, such as nitric oxide and superoxide dismutase, as well as reducing the levels of pro-inflammatory cytokines like TNF-α, IL-1β, and IL-6." (PMID 37653406, 2023). "The results showed that colitis was dramatically ameliorated in the XJS-treated rats as evidenced by relief of clinical symptoms and histopathological damages, downregulation of pro-inflammatory cytokines IL-6, IL-17 and TNF-α, and upregulation of anti-inflammatory cytokine IL-10." (PMID 37153794, 2023). "Careful examination revealed unexpectedly that Npr1−/− mice developed colitis characterized by shortened colon, evident colonic mucosal damage, increased histopathological score, and higher colonic expression of proinflammatory cytokines interleukin-1B (IL1B) and -6 (IL6)." (PMID 35794311, 2022). "Moreover, a previous study showed that oral administration of the AhR agonist β-naphthoflavone decreased DSS-induced colitis severity and the production of pro-inflammatory cytokines, such as tumor necrosis factor (TNF)-α, IL-6, and IL-1β, which was consistent with our results." (PMID 36613665, 2022). "Particularly, an anti-inflammatory effect of TGR5 activation by ligands such as BAR 501 through a reduction in IL6, TNFa, and INFy, an increase in IL10, and the promotion of macrophage differentiation from the M1 to the M2 phenotype has been observed in mice models of colitis." (PMID 35807844, 2022).
colitis (continued). "In addition, prophylactic administration of EGCG could reduce the levels of plasma IL-1β, IL-6, IL-8, and TNF-α in mice with colitis induced by DSS, indicating that EGCG can alleviate the symptoms of colitis, colonic injury, and inflammation." (PMID 35276917, 2022). "The decreased expression of proinflammatory cytokine and increased expression of anti-inflammatory cytokine were also observed in the miR-200b-3p- and miR-181b-5p-treated colitis groups, including IL-6, IL-1β and IL-10, but no significant changes in IL-22 was observed." (PMID 36176029, 2022). "DSS increases the production of pro-inflammatory mediators TNF-α, IL-1β, IL-6, IFN-γ and chemokine KC and macrophage inflammatory protein-2, which not only play important role in the pathogenesis of DSS-induced colitis, but also serve as crucial intervention targets for colitis." (PMID 36389828, 2022). "In this study, we used ELISA to detect the contents of cytokines IL-1β, IL-6, TNF-α, IL-12, and TGF-β in mouse intestinal tissue, and we found that QYJD could significantly reduce the contents of IL-1β, IL-6, TNF-α, and TGF-β in colon tissue of mice with colitis." (PMID 36523417, 2022). "Furthermore, the slight rise of pro-inflammatory factors like IL-6, CXCL1, and CXCL2 might suggest possible spontaneous colitis in a long observation period." (PMID 36425784, 2022). "In a rat model of DSS-induced colitis, the oral administration of Lf induced a significant increase in anti-inflammatory cytokines (IL-4 and IL-10) and a significant reduction in pro-inflammatory cytokines (TNF- α, IL-1β and IL-6), with a consistent improvement in disease severity." (PMID 35407131, 2022). "Colitis rats induced by 5% DSS and supplemented with 100 mg LBP/kg bw for 4 weeks reduces serum lipid peroxidation substance MDA levels, colonic TNF-α, serum IL-6 levels, and the expression of pain signaling proteins TRPV1 and TRPA1 in the colon, and enhance serum antioxidative CAT activity." (PMID 35269566, 2022). "In mice colitis models, we demonstrated that orally administrated of TDNPs 2 could ameliorate mice colitis and accelerate colitis resolution via regulating the expression of the pro-inflammatory cytokines, including TNF-α, IL-6, and IL-1β, and antioxidant gene, HO-1." (PMID 35488343, 2022). "The severe acute colitis in AKR1B8 KO mice is featured with high bacterial penetration into mucosa and distant organs, hyper-infiltration of basophils and neutrophils, and activation of innate TLR4 signaling pathway and subsequent production of inflammatory cytokines IL1β and IL6." (PMID 36518763, 2022). "These colitis mice also showed a shorter colonic length, increased colonic weight and index of colonic weight, DAI, and pathological damage score, as well as increased levels of pro-inflammatory cytokines TNF-α, IL-1β, IL-6, and IL-12p70, and decreased the level of anti-inflammatory cytokine IL-10." (PMID 36310616, 2022). "In addition, colitis mice that were administered BMVs from normal and DSS-miR-200b-3p feces showed reduced levels of inflammation-related parameters in the serum and colon, including decreased IL-6 and TNF-α levels and increased IL-10 levels." (PMID 36176029, 2022). "Ramulus mori polysaccharides inhibited the secretion of inflammatory cytokines IFN-γ and IL-6 and regulated intestinal microbiota abundance, including that of Firmicutes, Bacteroides, Myxospirillum, and Paraprevotella, and therefore, alleviated DSS-induced colitis in a mouse model." (PMID 35454671, 2022). "Exosomes from hucMSCs reduced the expression of the proinflammatory cytokines TNF-α, IL-1β and IL-6 in the colon in IBD mice, increased the expression of the anti-inflammatory cytokine IL-10 and attenuated the inflammatory response, thereby alleviating DSS-induced colitis in mice." (PMID 36045437, 2022).
colitis (continued). "Moreover, cholecystectomy also reduced mRNA levels of pro-inflammatory cytokines (Il1β, Il6, Tnfα); while it did not affect anti-inflammatory cytokines (Il4, Il10) in colonic tissues under colitis status." (PMID 36050867, 2022). "The oral GSK3-α/β and CDK9 inhibitor, ABC1183, led to a dramatic improvement in dextran sulfate sodium- and 2,4,6-trinitrobenzene sulfonic acid- induced colitis that was associated with suppression of TNF-α and IL-6, and no observed organ or hematological toxicity." (PMID 35660024, 2022). "Similarly, in the present study, we also found that the levels of serum IL-1β, IL-6, and TNF-α were increased in DSS-induced colitis, while LSE supplementation could decrease these inflammatory cytokines." (PMID 35059326, 2021). "However, it is unclear why reducing FAAH activity does not attenuate colitis-induced increases in IL-6, given what others have shown." (PMID 34916909, 2021). "After three cycles of DSS administration, mice with colitis showed reduced colon length (a marker of intestinal inflammation) as well as increased levels of DAI, MDA (a measure of the colonic oxidative insult), MPO (an index of neutrophil accumulation), and inflammatory factors (IL-1β and IL-6)." (PMID 34393786, 2021). "We demonstrated that both extracts, when administered orally, could reduce the elevated levels of pro-inflammatory cytokines, including TNF-α, IL-1β, and IL-6, in the Dextran Sodium Sulfate (DSS) colitis mouse model and effectively ameliorated the experimental colitis." (PMID 34940701, 2021). "A similar trend was observed in our previous studies, which revealed that mice with colitis subjected to voluntary moderate training or forced moderate training had significantly elevated adiponectin plasma levels, while plasma concentrations of leptin, TNF-α, IL-6 and IL-13 were markedly reduced." (PMID 33557311, 2021). "The present study confirms that HFD augmented the severity of experimental colitis as documented by the increased DAI index, the colonic tissue weight and upregulated colonic expression of proinflammatory biomarkers TNF-α, IL-1β and IL-6 mRNA compared to the mice fed an SD." (PMID 33557311, 2021). "Expression of Ifng, a cytokine involved in mediating colitis in the IL 10-KO model, trended toward increased expression, although this did not meet statistical significance, and expression of Il6, a cytokine with both pro- and anti-inflammatory effects in colitis, was not significantly elevated." (PMID 33826403, 2021). "Macroscopic and microscopic colitis in sedentary SD mice was accompanied by a significant decrease in CBF, and a significant increase in the colonic expression of tumor necrosis factor-alpha (TNF-α), IL-6, IL-1β and leptin mRNAs and decrease in the mRNA expression of adiponectin." (PMID 33557311, 2021). "Additionally, a curative study carried out with L. fermentum CECT5716 in the same TNBS model in rats showed its effect in the late phase of colitis, being able to decrease leukotriene B4 (LTB4) production, Il-6 expression, and Toll-like receptor (TLR)/MyD88 function." (PMID 33801082, 2021). "In addition to IL-6 and IL-1β, earlier studies reported TNF-α-induced epithelial barrier dysfunction in rat colon via downregulation of occludin and E-cadherin and in DSS-induced colitis in mice." (PMID 33669494, 2021). "Therefore, we analyzed the secreted pro-inflammatory cytokines in colonic tissue of mice and found that the DSS-induced increased secretion of IL-6, IL-1β, and TNF-α was significantly reduced by saffron (20 mg/kg), reducing the severity of the DSS-induced colitis." (PMID 34199466, 2021). "Supplementation of taxifolin significantly inhibited the secretions of tumor necrosis factor-α, interleukin (IL)-1β, and IL-6 and significantly increased the secretions of IL-10, secretory immunoglobulin A, superoxide dismutase, and immunoglobulins (IgA, IgG, and IgM) in DSS-induced colitis mice." (PMID 33664740, 2020).